ALB (albumin)
Diseases named in the same sentence as ALB in open-access papers (continued):
Sharing a sentence is not in itself a finding about the gene and the disease.
lung cancer (continued). "These patients are affected more by cachexia and lower albumin levels at the time of diagnosis in comparison to patients from earlier lung cancer stages, and this impacts any potential clinical validation of NPS in NSCLC." (PMID 38132225, 2023). "Researches about the association between serum albumin-to-globulin ratio (AGR) and the prognosis of lung cancer are limited." (PMID 37491191, 2023). "Considering the prognostic value of ALI for various tumors, especially lung cancer, and the evidence of BMI, albumin and NLR for tumor prognosis, we assumed ALI was a biomarker for disease status in GC." (PMID 35729545, 2022). "Another study showed that low nutritional and immunological status as assessed by the prognostic lymphocyte count calculated using serum albumin levels and peripheral lymphocyte counts predicts postoperative complications after lung cancer surgery." (PMID 36214634, 2022). "Although there are no specific laboratory markers for pancreatic CC, hemoglobin and albumin have been reported to be involved in gastrointestinal, gynecological, hematopoietic, lung cancer, and PC." (PMID 35804906, 2022). "However, future investigations are needed to further explore the biological role of albumin in the development of lung cancer and whether the molecular mechanisms underneath the albumin-inflammation association differ by race/ethnicity or socio-economic status." (PMID 35814479, 2022). "In this study, ultrasmall chelator-free 64Cu nanoclusters utilizing bovine serum albumin (BSA) as a scaffold for PET imaging in an orthotopic lung cancer model were developed." (PMID 35159648, 2022). "Our study was the first to demonstrate that albumin can be applied to predict the efficacy of immunotherapy in patients with lung cancer." (PMID 36540802, 2022). "Other studies have shown that perioperative changes in serum albumin are predictors of lung complications in patients with lung cancer and laparoscopic gastrectomy." (PMID 34409047, 2021). "The modified Glasgow prognostic score (mGPS), a representative maker based on CRP and albumin, has been shown to be a prognostic indicator for various types of cancer, including lung cancer." (PMID 33866376, 2021). "The antiproliferative effects of PAC, ExoPAC and FA-ExoPAC were determined against drug-sensitive and drug-resistant human lung cancer cells and compared with albumin-bound PAC (Abraxane)." (PMID 34359601, 2021). "The albumin-globulin ratio (AGR), calculated as serum albumin/(serum protein–serum albumin), has been reported to be a novel prognosticator of many diseases, such as lung cancer and microscopic polyangiitis." (PMID 34484470, 2021). "The 1887 lung cancer patients excluded due to missing serum albumin and/or alkaline phosphatase measurements had a significantly higher median age, lower TNM stage, and higher PS than the 7077 included patients." (PMID 34885242, 2021). "The advanced lung cancer inflammation index [ALI: body mass index × serum albumin/neutrophil-to-lymphocyte ratio (NLR)] reflects systemic host inflammation, and is easily reproducible." (PMID 34481329, 2021). "And CRP/ALB ratio has been used as a prognostic factor in variety of solid cancers including esophageal cancer, lung cancer, gastric cancer, colorectal cancer and so on." (PMID 34001160, 2021). "The bootstrap resampling variable selection method provided six variables: respiratory rate, body temperature, altered mentation at ED presentation, lung cancer, lactic acid, and albumin." (PMID 33308206, 2020). "Of physiological parameters, the albumin to creatinine ratio (ACR) in urine was much higher (733.7 ± 80 μg/mg) in the lung cancer mice than that (24.89 ± 1.8 μg/mg) in the sham group." (PMID 33260558, 2020). "We named this new prognostic scoring system the VitaL CLASS score (vital signs-lung cancer-lactate-albumin in septic shock)." (PMID 33308206, 2020).
lung cancer (continued). "Using a retrospective cohort study with a large number of patients, this study investigates the relationships between albumin‐to‐alkaline phosphatase ratio as a prognostic factor for patients with advanced non‐small cell lung cancer." (PMID 32691996, 2020). "Past studied have shown that pre-treatment hemoglobin/hematocrit and albumin are prognostic factors for outcomes among those with cancer and specifically, those with lung cancer." (PMID 32306924, 2020). "Nine out of 10 studies focusing on the relationship between ALB and lung cancer also demonstrated that the higher ALB was positively correlated with the survival rate." (PMID 32691996, 2020). "The high urinary albumin-to-creatinine ratio (ACR) was diagnosed as paraneoplastic nephrotic syndrome in those lung cancer mice." (PMID 33260558, 2020). "She had received two courses of chemotherapy with carboplatin and nanoparticle albumin-bound (nab)-paclitaxel for lung cancer until four months before admission, followed by two courses of nivolumab until one month before admission." (PMID 33029462, 2020). "Cationic bovine serum albumin (CBSA) has been utilized for the delivery of siRNA for the metastatic lung cancer therapy." (PMID 31035440, 2019). "A comparative analysis of blood samples (depleted of albumin and IgG) obtained from lung cancer patients before chemotherapy versus after a second cycle of chemotherapy was performed using two-dimensional difference gel electrophoresis (2D-DIGE)." (PMID 31622403, 2019). "Many studies have shown that serum albumin as an independent prognosticator of survival in lung cancer." (PMID 29728103, 2018). "Weekly albumin-bound paclitaxel is effective and well tolerated in the treatment of advanced lung cancer including all histological subtypes." (PMID 28738964, 2017). "A total of 1, 098 patients with lung cancer were diagnosed by pathology and tested the serum albumin and urea level in West China Hospital of Sichuan University during January 2008 to December 2013." (PMID 28302220, 2017). "The aim of this retrospective study is to observe the efficacy and safety of albumin-bound paclitaxel-based therapy in the treatment of lung cancer." (PMID 28738964, 2017). "Serum levels of SCC, Cyfra21-1, and CEA are markedly increased with increasing urinary albumin excretion, which affects the specificity for diagnosis for lung cancer." (PMID 28744310, 2017). "This study aims to identify the relationships between serum albumin and urea level and the clinical pathological characteristics and survival time in patients with lung cancer." (PMID 28302220, 2017). "There are publications demonstrating that serum albumin levels have considerable effects on prognosis not only in lung cancer but also in other organ cancers." (PMID 26782276, 2016). "Weight loss, lean body mass decrease, and hypermetabolism are highly correlated to both the elevated levels of proinflammatory cytokines, such as IL-1β, IL-6 and TNF-α and the decreased level of albumin in lung cancer patients." (PMID 23349693, 2013). "The advanced lung cancer inflammation index was calculated as BMI*ALB/NLR." (PMID 40297155, 2025). "The Advanced Lung Cancer Inflammation Index (ALI), which combines body mass index, serum albumin, and neutrophil–lymphocyte ratio, has been linked to outcomes in chronic diseases, but its relationship with bone turnover markers (BTMs) in OPF remains unclear." (PMID 41573203, 2025). "Similarly, other studies involving patients with gastric, colorectal, pancreatic, and lung cancers have indicated that a lower mGPS, also based on serum CRP and albumin levels, was associated with a better treatment response." (PMID 40627291, 2025). "Several prospective studies have found a negative correlation between serum albumin levels and lung cancer risk." (PMID 40165889, 2025).
lung cancer (continued). "The HALP(hemoglobin, albumin, lymphocyte, and platelet) score, which is calculated using hemoglobin, albumin, lymphocyte, and platelet levels, is one such index that has been studied in several cancers, including renal cell carcinoma, lung cancer, and gastric cancer." (PMID 40365347, 2025). "These bidirectional regulatory interactions among bilirubin, albumin, and estrogen constitute a complex physiological network that may influence lung cancer development in women." (PMID 40508934, 2025). "Since the ALBI index integrates both bilirubin and albumin concentrations, the inverse association observed between ALBI and lung cancer risk in men may reflect a physiological state characterized by improved antioxidant capacity and hormonal balance." (PMID 40508934, 2025). "One study in the USA found an inverse association between albumin levels and lung cancer risk for African Americans, but not for European Americans, although the number of patients was small in the latter group." (PMID 40941010, 2025). "Ongoing clinical trials of albumin NPs in lung cancer and gastric cancer." (PMID 39070787, 2024). "Besides the RDW–albumin ratio, Triglyceride–glucose index, and pan-immune-inflammation value explored in this study, other indices such as the Advanced Lung Cancer Inflammation Index (ALI) have also shown prognostic value in cardiovascular diseases." (PMID 39685462, 2024). "Additionally, serum albumin is also a valuable biomarker for a variety of respiratory disorders, including lung cancer, chronic obstructive pulmonary disease, acute pulmonary embolism, and bronchiectasis." (PMID 38835754, 2024). "We found that lung cancer CRA is primarily related to the patient's past surgeries, chemotherapy, KPS score, serum iron, CRP, albumin, and total cholesterol levels through the univariate analysis of clinical data and laboratory indices of 1040 lung cancer patients with CRA." (PMID 38562035, 2024). "Several previous studies have shown that perioperative albumin levels are significantly associated with postoperative complications in patients with malignancies, such as colorectal cancer, gastric cancer, and lung cancer, as well as in noncancer patients." (PMID 38773489, 2024). "The advanced lung cancer inflammation index (ALI) is determined by serum albumin (ALB), body mass index (BMI), and NLR, which constitute a composite index, and multiple studies have shown that ALI has good predictive value in assessing the survival prognosis of cancer patients." (PMID 38877553, 2024). "Pre-treatment BMI and albumin levels will affect the prognosis of patients with lung cancer." (PMID 37077828, 2023). "And the SOFA score, anion gap and albumin are the most important factors which impacted on the output of the machine learning models in predicting in-hospital mortality of critically ill patients with lung cancer." (PMID 36701342, 2023). "Low albumin levels have been confirmed to be a useful prognostic tool for lung cancer." (PMID 37491191, 2023). "In addition, lung cancer patients who smoked also tended to be older, alcohol drinkers, or had lower albumin and ALI." (PMID 36073671, 2023). "Higher albumin levels were also associated with decreased risk of lung cancer, although not significantly, among participants diagnosed ≤2 years after blood collection (ORT3 vs.T1 = 0.57, 95% CI: 0.27-1.18)." (PMID 35814479, 2022). "CAR, as a combination of the two indexes plasma CRP and albumin, may be used as a simple biomarker to predict the survival status of patients with lung cancer." (PMID 36684183, 2022). "Albumin and globulin play an important role in immunity and inflammation; therefore, several studies have been proposed the ratio of albumin to globulin ratio as a biomarker in gastric cancer and lung cancer." (PMID 35054370, 2022). "The current results indicated that high BMI is related to longer PFS in lung cancer patients treated with ICIs, which may be correlated with high levels of serum albumin and creatinine." (PMID 35902908, 2022).
lung cancer (continued). "C-reactive protein (CRP) and albumin can represent the inflammatory response and nutritional status in a better way, and studies have confirmed that high CRP and low albumin levels are significantly correlated with the poor prognosis of patients with lung cancer." (PMID 36684183, 2022). "Moreover, studies have shown that perioperative serum albumin changes are predictive factors of PPCs in patients with lung cancer." (PMID 35004710, 2021). "Concerning each cancer type, there was a linear association between albumin and liver cancer risk (p‐overall = 0.0002, p‐nonlinear = 0.1807), and a slightly significant association was also observed for lung cancer (p‐overall = 0.0456, p‐nonlinear = 0.2113)." (PMID 34041866, 2021). "Using this stratification system, which was similar to the categorization strategy used for the albumin-neutrophil combined prognostic grade in patients with lung cancer, we observed a significantly worse prognosis in the high-risk group than in the low-risk group." (PMID 33833991, 2021). "The inflammation‐based Glasgow Prognostic Score (GPS), is calculated by the C‐reactive protein (CRP) and albumin (Alb) levels and serves as a reliable long‐term prognostic indicator of solid cancers, including lung cancers; a higher GPS score denotes a worse prognosis." (PMID 33480111, 2021). "The PFS duration was significantly associated with the baseline neutrophil‐to‐lymphocyte ratio and the three‐week values for the modified Glasgow prognostic score, C‐reactive protein‐albumin ratio, prognostic nutrition index, and advanced lung cancer inflammation index." (PMID 33124197, 2021). "Similarly, studies have suggested that serum albumin reduction on the 1st day after surgery can be a predictor of PPCs in patients with lung cancer after thoracoscopic anatomy." (PMID 34409047, 2021). "A high Cav-1 level could contribute to the entry of albumin and nab-paclitaxel (albumin-bound paclitaxel) into H23 lung cancer cells, therefore, enhancing cell apoptosis; while drug resistance is shown in these cells following Cav-1 reduction." (PMID 31991790, 2020). "New scoring system for 28-day mortality was based on six variables (score range, 0–8): vital signs at ED presentation (respiratory rate, body temperature, and altered mentation), lung cancer type, and two laboratory values (lactate and albumin) in septic shock (VitaL CLASS)." (PMID 33308206, 2020). "Moreover, preoperative serum albumin (Alb) concentration has also been used to predict the survival outcomes for lung cancer (LC), GC and EC patients." (PMID 33392090, 2020). "Changes in body weight and serum albumin levels were investigated in a case–control study of patients with FN, and control patients without FN who were matched by age, gender, histopathology, and stage of lung cancer, at a ratio of 1:2." (PMID 33324729, 2020). "Even though the cause of death in our cohort was mostly due to progressive disease imitated in corticosteroid use and high CRP/Albumin, assessing the effect of treatment-related lymphopenia on survival in patients with better prognosis at early stage of lung cancer is encouraging." (PMID 32181373, 2020). "Similarly, increased levels of other extravasated plasma proteins, such as complement factor H or albumin, were previously observed in bronchial fluids from lung cancer patients." (PMID 25799154, 2015). "Serum C-reactive protein levels and plasma fibrinogen levels were significantly higher and serum albumin concentration was significantly lower in lung cancer patients with detectable serum IL-6 levels than in those without detectable serum IL-6 levels and in patients with benign lung diseases." (PMID 7734307, 1995).
lung cancer (continued). "Therefore, this study aimed to investigate whether pretreatment indicators, such as serum albumin (albumin) levels, affect length of hospital stay in older male patients with lung cancer receiving their initial inpatient chemotherapy." (PMID 40786260, 2025). "This study explores the association between the Advanced Lung Cancer Inflammation Index (ALI) and 30-day mortality in ICH patients, evaluating its prognostic value as a composite biomarker that integrates body mass index (BMI), serum albumin, and neutrophil-to-lymphocyte ratio (NLR)." (PMID 40791910, 2025). "Five biomarkers showed inverse causal relationships with lung cancer risk: total bilirubin with small cell lung cancer (SCLC), urate with non-small cell lung cancer (NSCLC), serum calcium with lung squamous cell carcinoma (LSCC), non-albumin proteins with LSCC, and total protein with LSCC." (PMID 39687887, 2024). "Consequently, based on the variable coefficients from the stepwise regression, a prognostic model for lung cancer-related oxidative stress score (OSS) was further developed: OSS=(ALB × (-0.4362)) + (BUN × (-0.2667)) + (TBIL × (-0.3965)) + (UA × 0.3770) + (LDH × (-0.2101)) + (Crs × 0.2679)." (PMID 39507753, 2024). "However, there were also several studies reporting nonsignificant associations between ALB and the prognosis of lung cancer, which is in accord with our findings." (PMID 36980604, 2023). "In addition, lung carcinoma tissues contain insoluble forms of human serum albumin." (PMID 35326173, 2022). "In a previous pilot study in patients undergoing pneumonectomy for lung cancer, we showed that underweight was associated with higher C-Reactive Protein (CRP) levels; we also found that systemic inflammation is associated with a lower plasmatic concentration of both albumin and prealbumin." (PMID 34572801, 2021). "Correlation analysis in the current study demonstrated that in lung cancer patients ANC and MPV were negatively weakly correlated with ALB and TP, respectively, which showed that the inflammatory stage of lung cancer might be related to nutritional insufficiency." (PMID 32377267, 2020). "As with many cancer types, cachexia and low protein-albumin levels may be observed in lung cancer." (PMID 26782276, 2016). "Background/Objectives: This study investigates the induction of cuproptosis in A549 lung cancer cells by doxorubicin (DOX) complexes and the development of pH-responsive bovine serum albumin (BSA)-based nanocarriers for their delivery." (PMID 42198219, 2026). "The inflammatory biomarkers included the neutrophil-percentage-to-albumin ratio (NPAR), advanced lung cancer inflammation index (ALI) and pan-immune-inflammation value (PIV)." (PMID 42255447, 2026). "The compounds were tested for their cytotoxic effects on A549 lung carcinoma cells and CCD-18Co fibroblasts, inhibition of topoisomerase I (Topo I), and binding interactions with human serum albumin (HSA)." (PMID 41673274, 2026). "This study investigated the association between eight inflammation-nutrition markers (NLR, LMR, PLR, SII, HALP, PNI, HRR, and ALB/GLB) and overall survival (OS) in 500 lung cancer patients." (PMID 40846746, 2025). "Background and Objectives: The Advanced Lung Cancer Inflammation Index (ALI), a composite marker integrating body mass index (BMI), serum albumin, and neutrophil-to-lymphocyte ratio (NLR), has demonstrated prognostic value in various cancers." (PMID 41303789, 2025). "The advanced lung cancer inflammation index (ALI), which integrates body weight, albumin levels, and the neutrophil-to-lymphocyte ratio (NLR), was initially designed to gauge systemic inflammation in cancer patients." (PMID 40655483, 2025). "When combined with novel indices like the Advanced Lung Cancer Inflammation Index (ALI), which integrates albumin and neutrophil-to-lymphocyte ratio, assessment of patient risk can be substantially enhanced without the need for complex or costly tools." (PMID 41156275, 2025).